RNU6-514P (RNA, U6 small nuclear 514, pseudogene)
Gene: Small nuclear RNA gene on chromosome 1 (23,162,704 to 23,162,810, forward strand). Ensembl gene ENSG00000206935.
Homologues: Orthologues: chimpanzee U6 (99% identical), macaque U6 (93% identical), guinea pig U6 (87% identical), dog U6 (84% identical), rabbit U6 (84% identical), guinea pig U6 (82% identical), mouse Gm23002 (82% identical), rat LOC120100169 (79% identical), pig U6 (78% identical). Paralogues in human: RNU6-47P (86% identical), RNU6-698P (86% identical), RNU6-1042P (85% identical), RNU6-15P (85% identical), RNU6-188P (85% identical), RNU6-19P (85% identical), RNU6-831P (85% identical), RNU6-1060P (84% identical), RNU6-1145P (84% identical), RNU6-116P (84% identical), RNU6-1316P (84% identical), RNU6-166P (84% identical), and 1287 more.